HGF (hepatocyte growth factor)
Diseases named in the same sentence as HGF in open-access papers (continued):
Sharing a sentence is not in itself a finding about the gene and the disease.
cancer (continued). "Applied to LUAD and LUSC datasets, our approach successfully identified a stable core set of pathogenic genes, including both highly expressed genes (e.g., CD74, HGF) and stably expressed genes (e.g., BRAF, KDM6A), which play critical roles in cancer progression." (PMID 40136480, 2025). "The observed increase in HGF expression, which may indicate a relative survival advantage of NHLFs, raises important questions about the TME and the complex interplay between cancer cells and stromal components." (PMID 41289612, 2025). "Although targeting HGF/c-MET has improved clinical outcomes in some cancers, monotherapy targeting HGF/c-MET has been unsuccessful in proving considerable clinical efficacy in several cancers." (PMID 39355533, 2024). "Pre-treatment circulating levels of serum IL-6, HGF, and CCR may serve as independent predictive and prognostic biomarkers in advanced cancer patients treated with ICIs-based systemic therapy." (PMID 38776028, 2024). "Based on the correlation of HAI-1 with CRC prognosis and cetuximab response in cancer databases and cell lines, we hypothesized that HAI-1 addition or overexpression would induce cetuximab sensitivity in HGF/MET-dependent cetuximab-resistant lines." (PMID 38212428, 2024). "As expected, HGF overexpression induced MAPK and PI3K signaling that may confer a proliferation and survival advantage to cancer cells." (PMID 38212428, 2024). "Cytokines such as hepatocyte growth factor (HGF), OPN, and stromal-derived factor 1α (SDF-1) up-regulate CD44v6 expression in CSC, which activates the Wnt/β-catenin pathway responsible for the promotion of cancer cell migration and metastasis in CRC." (PMID 38672650, 2024). "In conclusion, pre-treatment circulating levels of serum IL-6, HGF, and CCR may serve as independent predictive and prognostic biomarkers in advanced cancer patients treated with ICIs-based systemic therapy." (PMID 38776028, 2024). "While cancer organoid protocols share similarities, most include varying cocktails of growth factors and hormones, such as epithelial growth factor (EGF), WNT family member ligands, and/or hepatocyte growth factor (HGF)." (PMID 39286024, 2024). "This resistance may be mediated by the secretion of hepatocyte growth factor (HGF) by PDPN-positive CAFs, which activates the mesenchymal-epithelial transition (MET) signaling pathway and promotes cancer cell survival and growth." (PMID 39403603, 2024). "Here, we show for the first time that XP-C fibroblasts also play a major role in cancer cell invasion ex vivo and in vivo through the overexpression of Hepatocyte Growth Factor/Scatter Factor (HGF/SF) in the absence of genotoxic attacks." (PMID 39409898, 2024). "In inverse co-culture at both time points and standard co-culture at 72 h 26 genes were mutually expressed, among them genes of the KEGG pathway Proteoglycans in cancer, like Fibronectin 1 (FN1), Hepatocyte Growth Factor (HGF), Epiregulin (EREG) and Tissue Inhibitor of Metalloproteinases 1 (TIMP1)." (PMID 39098880, 2024). "Given its wide range of influence, the HGF/c-MET pathway has been the focus of numerous studies, aiming to reveal its complexities and the potential implications of its dysregulation in pathological conditions such as cancer, fibrosis, and other diseases." (PMID 38473413, 2024). "Here, we show for the first time that XP group C primary fibroblasts also play a major role in cancer cell invasion ex vivo and in vivo through the overexpression of Hepatocyte Growth Factor/Scatter Factor (HGF/SF) in the absence of genotoxic attacks." (PMID 39409898, 2024). "HGF activation induces integrin clustering, the recruitment of FAK and paxillin, and the transduction of downstream MAPK, PI3K, and Rho GTPase pathways which are important in cancer cell growth, invasion, and metastasis." (PMID 37550007, 2023). "Thus, the HGF-MET-MACC1 axis results in abnormal cell proliferation and an increased ability of cancer migration, invasion, and metastasis 18-20." (PMID 38021160, 2023).
cancer (continued). "Notably, 18 of the 74 FECGs enriched in the PI3K-AKT pathway are known cancer driver genes, which include 4 core members of oncogenic MET signaling (HGF, MET, PIK3R1, and PIK3CA)." (PMID 37668356, 2023). "Paracrine HGF induces YAP nuclear translocation by binding c-MET, resulting in the crosstalk between CAFs and cancer cells that HGF/c-MET-mediated induces the expression of stemness pluripotency markers such as NANOG, OCT4, and SOX2 in PC cells, as well as increased self-renewal ability." (PMID 37173787, 2023). "Here, we found that, despite that our compounds did not significantly affect the release of HGF in cancer cells or in lung fibroblasts, exposure to CM strongly increases HGF levels in culture medium, in both MDA-MB-231 and MRC5, as expected." (PMID 37686233, 2023). "Most cancer cells do not express HGF, and HGF is secreted mainly by cells of mesenchymal origin, acts in a paracrine manner on cells that express the c-MET receptor." (PMID 37828456, 2023). "In HNSCC, the hepatocyte growth factor/mesenchymal-epithelial-transition factor (HGF/c-MET) pathway promotes PI3K/Akt, RAS/MAPK, STAT3, and Src/NF-κB intracellular signaling, resulting in cancer cell proliferation and apoptosis avoidance, followed by extensive growth and metastasis." (PMID 37686523, 2023). "However, similar to targeting HGF/c-MET, clinical benefits of targeting the Hh pathway are limited to a few cancers such as BCC and MB." (PMID 37919751, 2023). "The findings suggest that targeting c-Met in the absence of functional HGF remains a viable therapeutic option to halt cancer progression." (PMID 36959792, 2023). "HGF/c-MET interactions are activated by stromal cell HGF, which produces a suitable microenvironment for cancer cell growth and invasion, and in an autocrine manner by c-MET produced by cancer cells." (PMID 37828456, 2023). "Additionally, we will explore the potential of simultaneously targeting the HGF/c-MET axis and Hh pathway as a rational approach for cancer therapy." (PMID 37919751, 2023). "Regarding other types of cancer, the best-characterized cytokines that mediate MSCs homing to tumors include CXCL12, IFN-γ, IL-6, IL-8 and TNF, as well as growth factors such as TGF-β, HGF, PDGF and VEGF." (PMID 37563650, 2023). "Aberration of the HGF/c-MET system is well documented in several human cancers, such as non-small cell lung cancer (NSCLC), squamous cell carcinoma of the head and neck (HNSCC) cancer, as well as other carcinomas." (PMID 35807022, 2022). "There are many signaling pathways, mediators, and downstream signaling proteins reported in angiogenesis-induced cancer: platelet-derived growth factor (PDGF), VEGF, fibroblast growth factors (FGF), hepatocyte growth factor (HGF), TKs, PI3K, MAPK, mTOR, Ras, and Raf." (PMID 36077338, 2022). "Tyrosine‐protein kinase Met—also known as c‐Met or HGFR—is a membrane receptor protein with associated tyrosine kinase activity physiologically stimulated by its natural ligand, the hepatocyte growth factor (HGF), and is involved in different ways in cancer progression and tumourigenesis." (PMID 35292998, 2022). "Met receptor and its ligand hepatocyte growth factor (HGF) are involved in several cellular signaling pathways that regulate proliferation, migration, and invasion, and aberrant Met signaling has been reported in several types of cancer." (PMID 35158995, 2022). "The proteoglycans in cancer pathway (ecb05205) regulates proteoglycans in the extracellular matrix, which influences the behavior of cancer cells and their microenvironment by interacting with various cytokines (e.g., TWIST2), growth factors (e.g., HGF) and cell surface receptors (e.g., EGFR)." (PMID 36553455, 2022). "Indeed, the role of aberrant HGF/SF and MET signalling in human cancer has been extensively investigated, and the use of MET agonists in regenerative medicine clearly must meet an adequate safety profile." (PMID 35905995, 2022).
cancer (continued). "Previous research has shown that HGF stimulates an increase in SOX2 and OCT-4 gene expression in cancer stem cells via the c-MET receptor and affects the maintenance of the stemness of human mesenchymal cells of bone marrow during long term cultures of over eight passages." (PMID 35883581, 2022). "Also, HGF derived from TME has reported to increase radioresistance and chemoresistance in several cancers." (PMID 35081970, 2022). "Dysregulation in HGF/c-MET signaling leading to uncontrolled proliferation, motility, invasiveness, and angiogenesis can play an essential role in the development, progression, and survival of cancer including HNSCC." (PMID 35081970, 2022). "In the meantime, cancer cells constantly receive and process signals from the microenvironment, among which many are growth factors produced by autocrine and/or paracrine mechanisms (e.g., EGF, FGF, HGF, VEGF)." (PMID 34970866, 2022). "Cancer cells treated with either inhibitor alone, without HGF, did not change migration and invasion." (PMID 36139568, 2022). "Based on these effects, HGF has been investigated as a biomarker for a variety of cancers, with most of these studies showing a negative correlation between plasma HGF levels and patient survival." (PMID 35216045, 2022). "The HGF/MET pathway is involved in cell motility, angiogenesis, proliferation, and cancer invasion." (PMID 34997350, 2022). "In present study, we reported that IFITM3 served as a novel modulator of HGF/MET-mediated AKT signaling that suppressed FOXO3 (Forkhead Box O3), consequently leading to c-MYC (MYC proto-oncogene) mediated cancer proliferation, migration, stemness and drug resistance." (PMID 35941699, 2022). "TAN-derived VEGF, HGF and MMP9 also make cancer cells more aggressive and facilitate angiogenesis." (PMID 36230676, 2022). "There were eight favorable prognostic genes and six poor prognostic genes incorporated in this signature, and a variety of OSRGs such as CD38, FOXO1, HGF, IL18BP, and TRPM2 were closely involved in the previous studies regarding cancer subtypes and immune landscape." (PMID 36561981, 2022). "Also, the proto-oncogene tyrosine–protein kinase Met (MET), together with hepatocyte growth factor (HGF), plays a role in embryogenesis, EMT, growth, and survival of cancer cells and stimulates metastasis." (PMID 36471782, 2022). "Furthermore, an in vitro study has demonstrated the ability of HGF to stimulate esophageal squamous cell carcinoma to express VEGF and IL-8 and to enhance the migration and invasion of cancer cells." (PMID 35626056, 2022). "CD44 and its multiple splice variants are involved in a variety of cancer mechanisms, including angiogenesis via the ERM-VEGFR axis, cell proliferation via the ERM-VEGFR-MAPK axis, metabolic shift in cancer cells via the SRC-AKT axis, and cancer cell invasion via the HGF-MET-PI3K-AKT axis." (PMID 34570764, 2021). "In addition, sEVs containing secretory EGFR derived from GC cells effectively activate hepatocyte growth factor, which in turn binds to c-MET receptors on migrating cancer cells to promote the homing of metastatic cancer cells." (PMID 33926452, 2021). "Reportedly, several RTKs, including receptors for epidermal growth factor (EGF), hepatocyte growth factor (HGF), platelet-derived growth factor (PDGF), or nerve growth factor, are positively or negatively regulated by the expression of gangliosides in cancer cells." (PMID 34064863, 2021). "Even more, CAFs could activate MAPK and PI3K-AKT signaling pathways in cancer cells, promoting the resistance to RAF inhibitors by secreting HGF." (PMID 33669949, 2021). "HGF-induced c-Met activation triggers downstream the PI3K/Akt pathway, enabling cancer progression." (PMID 34503172, 2021). "Neutralizing antibodies against five arbitrarily selected pleiotropic proteins present in MAs (TGF-β1, HGF, EGF, IGF-1, GRO-1) were used to check whether inhibition of these agents translates to decreased adhesion of cancer cells to PMCs or PFBs." (PMID 33921783, 2021).
cancer (continued). "However, Abs and Nbs tend to be initially developed to demonstrate anti-cancer potential, for example, EGRF, hepatocyte growth factor (HGF) and death receptor 5 (DR5)." (PMID 34575943, 2021). "The activated PSCs also secrete growth factors, such as hepatocyte growth factor (HGF), insulin growth factor-1 (IGF-1), platelet-derived growth factor (PDGF), and stromal cell-derived factor-1, creating a favorable environment for cancer cell growth." (PMID 34572031, 2021). "Although HGF/c‐MET pathway was deemed as a promising therapeutic target, numerous investigations have proven that inhibition of HGF or c‐Met TKI was not an effective and practical therapeutic strategy in suppressing multiple human cancers." (PMID 33751856, 2021). "The HGF/MET axis is involved in a series of biological responses, such as proliferation, angiogenesis, migration, invasion, metastasis, and survival, thus contributing to tumorigenesis, development, and progression in different human cancer types." (PMID 34956177, 2021). "We found that HGF/c-MET and immune regulation levels are highly specific in different cancers." (PMID 34261467, 2021). "In addition to distinguishing between tumors and normal samples, we also attempted to compare the relationship between HGF/c-MET, immune infiltration and survival outcomes in patients with cancer." (PMID 34261467, 2021). "MET is an RTK for hepatocyte growth factor (HGF), which plays key roles in transducing signals that lead to increased cancer cell invasion and metastasis, and much signalling downstream of MET is thought to be mediated via activation of the oncogene activator of transcription, STAT3." (PMID 34819513, 2021). "Moreover, while PSCs strongly express hepatocyte growth factor (HGF), its receptor c-Met is mainly expressed by cancer cells." (PMID 33546284, 2021). "Notably, cabozantinib, a multikinase inhibitor, targets not only HGF/c-Met but also the VEGF/VEGFR2 pathway, both involved in Treg accumulation in the context of cancer." (PMID 34771724, 2021). "HGF is a negative cytokine of cancer immunotherapies involved in reactive recruitment of neutrophils, which can impair T cell expansion and effector function, but significantly corrected with good prognosis." (PMID 33648605, 2021). "Interestingly, positively correlated loci represented cancer driver genes (MYC, PRKCD, RB1, CDK6), molecules involved in immune response (MALT1, PIK3CG), as well as cellular and hormonal signaling (HGF, PTPN13, IGF1, SMAD1, ESR1, CTGF)." (PMID 34368147, 2021). "Cancer-associated fibroblasts (CAFs) secrete growth factors, e.g., hepatocyte growth factor (HGF), epidermal growth factor (EGF) and cytokines, e.g., interleukin 6 (IL-6), which activate oncogenic signaling pathways in cancer cells, resulting in chemoresistance." (PMID 33918653, 2021). "Hepatocyte growth factor (HGF) binds to the c-mesenchymal-epithelial transition (C-MET) receptor and activates downstream signaling pathways, playing an essential role in the development of various cancers." (PMID 34261467, 2021). "Furthermore, CAFs produce a variety of humoral factors including HGF and PDGF-C, which activate tyrosine kinase signaling in neighboring cancer cells, thereby suppressing their sensitivity toward molecular targeted drugs against EGFR, BRAF, and VEGF." (PMID 34436224, 2021). "In response to intra-tumoural hypoxia, cancer cells express hypoxia-inducible factor-1α (HIF-1α), which induces the expression of the pro-angiogenic vascular endothelial growth factor (VEGF), MET and HGF." (PMID 33526881, 2021). "Thus, several MET-targeting agents, including HGF and MET antibodies, as well as small molecule kinase inhibitors, are currently envisaged as anti-cancer therapeutics." (PMID 34925346, 2021). "The HGF/c-Met pathway is upregulated in many different cancer types but the influence of this pathway on Treg development in cancer has to our knowledge not been explored." (PMID 34771724, 2021).